BCYRN1 (brain cytoplasmic RNA 1)
Synonyms: BC200; BC200a; NCRNA00004; LINC00004
Gene: Long non-coding RNA gene on chromosome 2 (47,335,315 to 47,335,514, forward strand). Ensembl gene ENSG00000236824.
Diseases named in the same sentence as BCYRN1 in open-access papers:
BCYRN1 is named in the same sentence as 59 diseases in open-access papers, as found by Europe PMC text mining. Sharing a sentence is not in itself a finding about the gene and the disease. The quoted sentences say what the papers report.
breast carcinoma (23 papers, 2013 to 2026). "Brain cytoplasmic RNA 1 (BCYRN1), also known as BC200, has emerged as a valuable prognostic biomarker in several solid tumors, such as non-small cell lung cancer 20, breast cancer 21, liver cancer 22, and so on." (PMID 33391513, 2021). "Recently, increasing studies showed that BCYRN1 is abnormally overexpressed in various types of human tumor tissues such as lung cancer, breast cancer, esophageal squamous cell carcinoma, colorectal cancer, cervical cancer and glioma." (PMID 31652309, 2019). "In breast cancer patients, levels of BCYRN1 expression were significantly increased in patients with ER-positive expression." (PMID 31652309, 2019). "Recently, high levels of BCYRN1 in breast cancer tissues, esophageal squamous cell carcinoma tissues and non-small-cell lung cancer tissues have been observed." (PMID 29435146, 2018). "Studies show that BCYRN1 is overexpressed in non-small-cell lung cancer, hepatocellular carcinoma, colorectal cancer, bladder cancer, esophageal squamous cell carcinoma, gastric cancer, cervical cancer, ovarian cancer, and breast cancer tissues compared to matched normal tissues." (PMID 35874631, 2022). "Moreover, we found BCYRN1 could also evade serum starvation induced apoptosis, consistent with its role of regulating apoptosis in breast cancer cells." (PMID 29435146, 2018). "The lncRNA BC200, also called brain cytoplasmic RNA 1 (BCYRN1), is upregulated in luminal breast cancer." (PMID 28959047, 2017).
glioma (21 papers, 2017 to 2025). A benign or malignant brain and spinal cord tumor that arises from glial cells (astrocytes, oligodendrocytes, ependymal cells). "Gain-of-function and loss-of-function experiments demonstrated that BCYRN1 inhibited the occurrence and development of glioma in vitro and in vivo." (PMID 32978519, 2020). "Overall, our data presented that the reduced expression of BCYRN1 was associated with poor patient outcome in glioma." (PMID 32978519, 2020). "However, other mechanisms underlying the downregulation of BCYRN1 in glioma need to be further investigated in our future studies." (PMID 32978519, 2020). "Previous studies have illustrated that lncRNA H19 activates the VEGF signaling pathway via sparing miR-138 to promote glioma angiogenesis, and that lncRNA BCYRN1 regulates the PTEN/AKT/p21 pathway to inhibit glioma tumorigenesis." (PMID 37934582, 2023). "LncRNA brain cytoplasmic RNA 1 (BCYRN1) can suppress glioma tumorigenesis by binding with miR-619-5p to adjust CUE domain containing 2 (CUEDC2) expression and the PTEN/ AKT/p21 pathway." (PMID 35156508, 2022). "Except for gliomas and ovarian cancer, BCYRN1 is highly expressed in most malignancies, and the oncogenic mechanisms need future investigation." (PMID 35874631, 2022). "Functionally, they showed that BCYRN1 overexpression can repress the proliferation and migration of glioma cells, while its knockdown has opposite effects." (PMID 33995499, 2021). "lncRNA brain cytoplasmic RNA 1 (BCYRN1) acts as a ceRNA that suppresses glioma progression accompanied by the inhibition of Akt signaling." (PMID 34202078, 2021). "Previous studies have revealed that miRNAs, such as miR-125-5p, miR-149 and miR-490-3p, act as targets of BCYRN1 in hepatocellular carcinoma, human glioma and lung cancer, respectively." (PMID 32944001, 2020). "In conclusion, our results indicated that PTEN/AKT signaling participated in BCYRN1-mediated inhibition of glioma progression via miR-619-5p/CUEDC2 axis." (PMID 32978519, 2020). "Our study revealed a mechanism for BCYRN1 that competitively bind miR-619-5p, in turn, suppressed glioma proliferation, migration through inactivating the CUEDC2/PTEN/AKT/p21 pathway." (PMID 32978519, 2020). "Collectively, these results in vitro and in vivo strongly suggested that BCYRN1 was a potential tumor suppressor in glioma." (PMID 32978519, 2020). "In this study, we found that lncRNA BCYRN1 was significantly lower in glioma than normal brain tissues and it was negatively correlated with glioma grade." (PMID 32978519, 2020). "Taken together, these data provided evidences that inhibition glioma progression of BCYRN1 was primarily dependent on the miR-619-5p/ CUEDC2 axis." (PMID 32978519, 2020). "In this study, we investigated the expression profiling of lncRNAs and identified a most downregulated lncRNA called BCYRN1 in glioma from RNA-seq." (PMID 32978519, 2020). "We believe that it is the first comprehensive characterization of BCYRN1 function and mechanism in glioma." (PMID 32978519, 2020). "In this study, we showed that CUEDC2 was downregulated in glioma and the lower expression was more likely to be poor overall survivals, which supported that reduced level of BCYRN1 was correlated with poor prognosis." (PMID 32978519, 2020). "We found that the CUEDC2 level was positively correlated with the BCYRN1 level in the glioma tissues." (PMID 32978519, 2020). "Among them, BCYRN1 was the most downregulated lncRNA, and its low expression positively correlated with glioma progression." (PMID 32978519, 2020). "Our findings demonstrated that the role of the regulatory network between BCYRN1/miR-619-5p/CUEDC2 in glioma was achieved by affecting PTEN/AKT signaling pathway activity." (PMID 32978519, 2020).
glioma (continued). "Taken together, our results indicated BCYRN1 served as a sponge for miR-619-5p in the regulation of glioma progression." (PMID 32978519, 2020). "Taken together, these data suggested that BCYRN1 downregulation was common in glioma tissues and was correlated with poor prognosis." (PMID 32978519, 2020). "In conclusion, we performed high-throughput RNA sequencing to uncover a downregulated lncRNA BCYRN1 in glioma and verified with clinical glioma samples." (PMID 32978519, 2020). "Our results indicate that BCYRN1 exerts as a tumor suppressor in glioma and has the potential to be the promising therapeutic target for glioma diagnosis, therapy, and prognosis." (PMID 32978519, 2020). "Functionally, BCYRN1 overexpression inhibited cell proliferation, migration in glioma cell lines, whereas BCYRN1 depletion resulted in the opposite way." (PMID 32978519, 2020). "Based on the fact that inactivation of the PTEN signaling pathway, frequently found to be disrupted in human glioma, we suspected that there were some other miRNAs or other mRNA targets of BCYRN1, contributing to the effect of BCYRN1, when PTEN was lost." (PMID 32978519, 2020). "BCYRN1 functioned as a ceRNA to inhibit glioma progression by sponging miR-619-5p to regulate CUEDC2 expression and PTEN/AKT/p21 pathway." (PMID 32978519, 2020). "Mechanistically, miR-619-5p specifically targeted the CUE domain containing protein 2 (CUEDC2), and BCYRN1/miR-619-5p suppressed glioma tumorigenesis by inactivating PTEN/AKT/p21 pathway in a CUEDC2-dependent manner." (PMID 32978519, 2020). "BCYRN1 can also inhibit glioma progression by sponging miR-619-5p." (PMID 40764575, 2025). "Additionally, the reduced expression of BCYRN1 increases the proliferation and migration of glioma cells, resulting in unfavorable outcomes in glioma patients." (PMID 35847925, 2022). "In this study, it was confirmed that miR-619-5p was the direct target gene of BCYRN1, further elucidating that miR-619-5p specifically targeted the CUE domain of protein 2 (CUEDC2), while BCYRN1/miR-619-5p inhibited glioma by inactivating the PTEN/AKT/p21 pathway in a CUEDC2-dependent manner." (PMID 36124026, 2022). "Two studies showed a link between BCYRN1 expression and gliomas." (PMID 35874631, 2022). "Future studies could reconcile the difference between these studies and shed light on the exact role of BCYRN1-mediated ceRNETs in glioma progression." (PMID 33995499, 2021). "BCYRN1, as the most downregulated lncRNA in glioma, was chosen for further studies." (PMID 32978519, 2020). "In this study, we found that miR-619-5p could promote cell proliferation and migration in glioma and sponged by BCYRN1." (PMID 32978519, 2020). "All these findings suggested BCYRN1 acted as a ceRNA for miR-619-5p in glioma." (PMID 32978519, 2020). "Our results indicated that BCYRN1 exerted tumor suppressor potential and might be a candidate in the diagnosis and treatment of glioma." (PMID 32978519, 2020). "Next, we confirmed the downregulated expression of BCYRN1 in 22 normal tissues and 111 glioma tissues (46 Grade I and II, 65 Grade III and IV) by RT-qPCR, and found that the expression of BCYRN1 was significantly lower in glioma tissue, especially reduced with advanced glioma grade." (PMID 32978519, 2020). "In addition, we assessed the correlation between BCYRN1 expression and prognosis of glioma patients." (PMID 32978519, 2020). "More importantly, upregulation of BCYRN1 could partially rescue the promotive effects of miR-619-5p on cell growth and migration, and the reductive effect of miR-619-5p on cell apoptosis in glioma." (PMID 32978519, 2020). "Our results revealed the clinical significance of BCYRN1 and indicated that BCYRN1 might be a candidate in diagnosis and treatment of glioma." (PMID 32978519, 2020). "Differential RNA transcripts and BCYRN1 were identified by RT-qPCR in glioma samples and controls." (PMID 32978519, 2020). "Lower BCYRN1 expression was related to poor prognosis of glioma patients." (PMID 32978519, 2020).
glioma (continued). "In addition, our study revealed a mechanism that BCYRN1 competitively bind miR-619-5p to regulate glioma progression through inactivating the CUEDC2/PTEN/AKT/p21 pathway." (PMID 32978519, 2020). "Among them, BCYRN1 was the most significantly downregulated lncRNA in glioma." (PMID 32978519, 2020). "Meanwhile, ablation of BCYRN1 could partially rescue the reductive effects of miR-619-5p on cell growth and migration, and the inductive effect of miR-619-5p on cell apoptosis in glioma." (PMID 32978519, 2020). "Furthermore, the miR-619-5p level was negatively correlated with the lncRNA BCYRN1 level in the glioma tissues." (PMID 32978519, 2020). "However, as a lncRNA derived from brain cytoplasm, the expression and function of BCYRN1 in glioma remain unknown." (PMID 32978519, 2020). "Furthermore, five kinds of glioma cell lines were tested the endogenous expression level of BCYRN1." (PMID 32978519, 2020). "Various lncRNAs were found to be aberrantly expressed in glioma, such as lncRNA PVT1, lncRNA BCYRN1 and lncRNA DGCR5." (PMID 38730506, 2024). "Brain Cytoplasmic RNA 1 (BCYRN1) binding with miR-619-5p can regulate CUE Domain Containing 2 (CUEDC2) expression and the PTEN/AKT/p21 pathway to inhibit glioma tumorigenesis." (PMID 37239411, 2023). "lncRNA BCYRN1 plays a ceRNA role by regulating CUEDC2 expression and PTEN/AKT/p21 pathway through sponge miR-619-5p, thereby inhibiting glioma development." (PMID 37252659, 2023). "Here, we uncovered a differentially expressed lncRNA called brain cytoplasmic RNA 1 (BCYRN1), and elucidated its function and molecular mechanism in the progression and development of glioma." (PMID 32978519, 2020). "This research indicated that the lncRNA brain cytoplasmic RNA 1(BCYRN1)acts as a tumor suppressor and may help diagnose and treat glioma." (PMID 35619711, 2022). "High expression of BCYRN1 acts as a ceRNA, sponging miR-619-5p to regulate the expression of CUE domain-containing protein 2 (CUEDC2) and the PTEN/AKT/p21 pathway, ultimately inhibiting cell proliferation and migration of glioma cell lines, which offers new insights for glioma treatment." (PMID 38967893, 2024). "Moreover, another research discovered that lncRNA brain cytoplasmic RNA 1(BCYRN1) served as a miR-619-5p sponge to regulate the cue domain containing 2(CUEDC2) expression in the PTEN/AKT/p21 pathway; this combination reduced glioma development." (PMID 35619711, 2022). "To explore the mechanism of BCYRN1/miR-619-5p in glioma progression, we performed comprehensive bioinformatic analysis using four datasets and found that 44 mRNAs might be the potential targets of miR-619-5p including CUEDC2, which was reported to be a tumor suppressor in glioma." (PMID 32978519, 2020).
Alzheimer disease (20 papers, 2006 to 2025). A progressive, neurodegenerative disease characterized by loss of function and death of nerve cells in several areas of the brain leading to loss of cognitive function such as memory and language. "In addition, aberrant BCYRN1 expression is also related to the neurodegeneration underlying Alzheimer's disease." (PMID 35874631, 2022). "Gene BCYRN1 is involved in the regulation of synaptogenesis, and there have been several literatures linking BCYRN1 and Alzheimer’s disease, a neurological disease, which implies the possible association between BCYRN1 and ASD." (PMID 33519924, 2020). "Primate‐specific brain cytoplasmic RNA BC200 (or BCYRN1) and its rodent orthologue (BC1) are cytoplasmic anti‐sense lncRNAs highly expressed in the brain and have been implicated in Alzheimer's disease (AD)." (PMID 32100288, 2020). "BCYRN1 encodes a neural small non-messenger RNA, is a member of the family of interspersed repetitive DNA, which has been reported to play a role in Alzheimer’s diseases and cancers." (PMID 27527274, 2016). "The lncRNAs BC200 (brain cytoplasmic RNA 1) and BACE1-AS are associated with Alzheimer’s disease; Thus, regulation by these lncRNAs may play a key role in human disease." (PMID 25764159, 2015). "Although this regulatory RNA class is very novel and therefore remains uncharacterized, in normal aging, cortical BCYRN1 levels typically decline and are reduced by >60% after age 48, but in Alzheimer’s disease brains, BCYRN1 levels have been documented to increase." (PMID 24244371, 2013). "The brain cytoplasmic RNA 1 lncRNA (BCYRN1, also referred to as BC200) gene is predominantly expressed in neural tissues and shows an elevated level in variety of tumor types and in Alzheimer's disease (AD) brain samples." (PMID 29850016, 2018).
lung cancer (16 papers, 2014 to 2025). A malignant neoplasm involving the lung. "Genes such as SYT13 and BCYRN1 were responsible for invasion and migration of many cancer cells such as gastric cancer and lung cancer, but these genes may be associated with invasion and migration of GBM cells." (PMID 31137733, 2019). "Other lncRNAs involved in promoting metastasis in lung cancer include chromatin-associated RNA 10 (CAR10) and brain cytoplasmic RNA 1 (BCYRN1)." (PMID 36765679, 2023). "Three studies included in the meta-analysis reported increased expression of BCYRN1 in lung cancers, which correlated with poor outcomes." (PMID 35874631, 2022). "It has been reported that BCYRN1 is highly expressed in various tumour tissues, such as hepatocellular carcinoma, gastric cancer, and lung cancer but is expressed at lower levels in healthy control (HC) tissues." (PMID 32944001, 2020). "Up to now, the prognostic value of BCYRN1 expression was investigated in esophageal squamous cell carcinoma, colorectal cancer and lung cancer." (PMID 31652309, 2019). "LncRNA BCYRN1 (BCYRN1) is a newly identified brain cytoplasmic lncRNA with 200 nucleotides that was discovered to be highly expressed in tumour tissues, including those of hepatocellular carcinoma, gastric cancer and lung cancer." (PMID 32944001, 2020). "Moreover, BCYRN1 could also regulate cell metastasis in lung cancer." (PMID 37143472, 2023). "In lung cancers, significantly dysregulated lncRNAs have been reported, and many of them, e.g., PANDAR, DLX6-AS1, BCYRN1, HNF1A-AS1, ANRIL, MEG3, and others, are involved in lung cancer pathogenesis, cell proliferation, invasion and metastasis, and drug resistance." (PMID 27322209, 2016). "Moreover, BCYRN1 could accelerate glycolysis and tumor progression via miR-149/PKM2 axis in lung cancer." (PMID 37143472, 2023).
non-small cell lung carcinoma (12 papers, 2015 to 2025). A group of at least three distinct histological types of lung cancer, including non-small cell squamous cell carcinoma, adenocarcinoma, and large cell carcinoma. "On the other hand, decreased BCYRN1 expression reduces cell activity in hepatocellular carcinoma, gastric cancer, and non-small cell lung cancer." (PMID 38892143, 2024). "For example, on the basis of published literature, BCYRN1 promoted cells metastasis of non-small-cell lung cancer through up-modulating MM9 and MMP13." (PMID 31920461, 2020). "For example, BCYRN1 has been identified to promote tumor growth and regulate metastasis in some cancers, such as non-small-cell lung cancer, colorectal cancer and so on." (PMID 31920461, 2020). "For example, BCYRN1 has been demonstrated to induce the proliferation and migration of non-small cell lung cancer (NSCLC) cells and play an important role in NSCLC progression." (PMID 31787106, 2019). "Several studies have shown that BCYRN1 expression is significantly increased in a variety of tumors and has been shown to be a biomarker for these tumors, including colorectal cancer, hepatocellular carcinoma, bladder cancer and non-small-cell lung cancer." (PMID 40764575, 2025). "Moreover, the promotion of glycolysis and tumor progression in non-small cell lung cancer (NSCLC) are observed as the result of BCYRN1 overexpression." (PMID 34489556, 2022). "In non-small cell lung cancer, Hu and Lu found c-MYC activated BCYRN1 to promote tumor cell metastasis through up-regulating MMP-9 and MMP-13." (PMID 31652309, 2019). "In non-small-cell lung cancer cells, the number of migrated and invaded cells and the expression of metastasis-supporting proteins MMP9 and MMP13 changed with the regulation of BCYRN1." (PMID 29435146, 2018).